GAS5 (growth arrest specific 5)
Diseases named in the same sentence as GAS5 in open-access papers (continued):
Sharing a sentence is not in itself a finding about the gene and the disease.
tumor (continued). "One mechanism shows that overexpressed GAS5 acts as a sponge via binding with and downregulation of miR-21, amplify-function mutations in PTEN, and promote tumor apoptosis; knocking out GAS5, in contrast, increases the proportion of S and G2 cancer cells, thereby promoting proliferation." (PMID 35837102, 2022). "miR-196a binds to GAS5 and down-regulates GAS5 levels, reducing its anti-tumor effect considerably." (PMID 35241975, 2022). "Then, GAS5 was found to be aberrantly expressed in many cancers and diseases, and the abnormal expression affected the biological characteristics of them, including cell proliferation, tumor growth, and metastasis." (PMID 36062165, 2022). "It was not the only pathway for GAS5, miR-21, and LIFR to inhibit the tumor cells, and one study reported that overexpression of GAS5 could inhibit cell proliferation and promote apoptosis by inhibiting miR-182-5p expression." (PMID 36062165, 2022). "GAS5 performs a tumor-suppressor through various mechanisms." (PMID 36362925, 2022). "In the subgroup analyses in the EGFR wild type population, the presence of GAS5 SNP rs145204276 Ins/Del + Del/Del may be correlated with an advanced tumor stage (p = 0.014) and distal metastases (p = 0.020) in non-smoker individuals." (PMID 36011604, 2022). "It has been suggested that GAS5 modulates miR-21/RECK to increase the radiation sensitivity of tumor cells, and could therefore also serve as a target for improving the effect of radiotherapy." (PMID 35241975, 2022). "For instance, GAS5 was identified as a potential tumor suppressor in glioma." (PMID 35782387, 2022). "GAS5 lncRNA is mainly regarded as a tumor suppressor in human cancers." (PMID 36119500, 2022). "The results indicated that tumors from the lncRNA GAS5-transfected GH3 cells grew more slowly than those from the control group during the entire tumor growth period, while miR-27a-5p mimics or silenced CYLD attenuated the effect of lncRNA GAS5 on tumor growth." (PMID 35435104, 2022). "GAS5 could suppress the decrease of LIFR caused by miR-21 and rescue the function of LIFR on tumor cell viability." (PMID 36062165, 2022). "The main finding of our study is that GAS5 a well‐established tumor suppression lncRNA in different types of human malignancies may also participate in MG." (PMID 34936242, 2022). "In cancer biology, it has been reported that GAS5 expression was negatively correlated with IL‐10 expression, and GAS5 may inhibit tumor growth by inhibiting IL‐10 secretion." (PMID 34936242, 2022). "The lncRNA growth arrest-specific transcript 5 (GAS5) is a tumor suppressor in multiple cancers." (PMID 35159386, 2022). "Meanwhile, the high expression of lncRNA-GAS5 was correlated with tumor stage (TNM), overall survival (OS), disease-free survival (DFS) and metastasis, suggesting that GAS5 may be a potential diagnostic and prognostic biomarker in HCC." (PMID 35936671, 2022). "On the contrary, the combined effect of EGFR wild type and GAS5 SNP rs145204276 Ins/Del + Del/Del increases neither the percentage of poorly differentiated tumor cells, nor the cell differentiation of the EGFR mutation type." (PMID 36011604, 2022). "It has been shown that GAS5 is downregulated and exerted a tumor-suppressive role in diverse cancers, including gastric cancer, non-small cell lung cancer, ovarian cancer, cervical cancer, gliomas, bladder cancer, renal cell carcinoma, and hepatocellular carcinoma." (PMID 34760707, 2021). "Thus, our finding on the lower levels of lncRNA GAS5 in exosomes from sera of CRC patients is consistent with the tumor-suppressive function of lncRNA GAS5." (PMID 34571795, 2021). "In addition, one of the main proposed mechanisms with which GAS5 exerts its tumor suppressor role is through acting as an endogenous sponge for the oncogenic miR-222." (PMID 35054253, 2021). "Interestingly, decreased expression of the oncosupressive lncRNA GAS5 is correlated with tumor development and worse clinical outcome in CC patients." (PMID 34026616, 2021).
tumor (continued). "GAS5 is a pivotal factor in the proliferation of CSCs, and thus to tumor promotion and metastasis." (PMID 34425750, 2021). "Tumor size was suppressed obviously after GAS5 overexpression treatment." (PMID 33976738, 2021). "GAS5 was believed to be a tumor suppressor in colorectal cancer." (PMID 33976738, 2021). "In contrast, the tumor suppressive lncRNA GAS5 (growth-arrest-specific transcript 5) could suppress proliferation, migration, invasion, and epithelial-mesenchymal transition (EMT) in OSCC." (PMID 34063159, 2021). "Next, this investigation sought to determine whether the lncRNAs PARTICLE and GAS5 are expressed in U87MG given their recognized role in tumor activation and repression respectively." (PMID 34207434, 2021). "Besides acting as a tumor suppressor, GAS5 was also found to confer pharmacogenomic significance in various types of cancer." (PMID 34094978, 2021). "GAS5 acts as a tumor suppressor in most neoplastic diseases." (PMID 33391419, 2021). "The lower expression of noncoding RNA growth arrest-specific transcript 5 (GAS5) in circulating exosomes (Exo-GAS5) could be a noninvasive blood-based tumor marker for early-stage NSCLC identification." (PMID 33504342, 2021). "We chose hFOB 1.19 and U2OS cells for further mechanistic studies, as these cells were found to be the ones with highest endogenous GAS5 levels, and we wanted to study the implications of downregulating GAS5 levels as would normally happen in tumor development and/or cancer metastasis." (PMID 34386496, 2021). "Additionally, GAS5 overexpression in TAMs leads to decreased tumor cell migration, whereas GAS5 knockdown reverses this effect." (PMID 34439281, 2021). "The results confirmed that lncRNA GAS5 can enhance survival and tumor sensitivity to PTX and CIS." (PMID 34202777, 2021). "On the contrary, Rictor down-regulated MEG3 and GAS5, both of which are tumor suppressive lncRNAs." (PMID 34540654, 2021). "GAS5 was also reduced in NSCLC tissue samples and negatively associated with tumor characteristics." (PMID 33418541, 2021). "In contrast, the lncRNA GAS5 works as a tumor suppressor in multiple cancers." (PMID 34820419, 2021). "GAS5 is a tumor suppressor lncRNA with acknowledged roles in several tissues." (PMID 34368145, 2021). "Upon restoring GAS5 expression, an inhibition of cell growth while an enhancement in cell apoptosis were observed, suggested that GAS5 functioned as a tumor suppressor and could reverse DOX resistance in GC cells." (PMID 34345204, 2021). "In vivo, GAS5 upregulation inhibited remarkably NSCLC/DDP cell tumor growth." (PMID 33418541, 2021). "Above all, the GAS5 indeed did suppress the growth of metastatic tumor cells in vivo." (PMID 33976738, 2021). "In contrast, the GAS5 lncRNA evaluated by us is a tumor suppressor." (PMID 34386496, 2021). "All findings demonstrate that GAS5 is a tumor suppressive lncRNA." (PMID 34439315, 2021). "In addition, GAS5 can regulate the transcriptional activity of other receptors, such as androgen and progesterone and has been suggested as a potential tumor suppressor due to its pro-apoptotic function." (PMID 34717732, 2021). "GAS5 is a tumor suppressor that is downregulated in HCC, GC and ovarian cancer." (PMID 34425750, 2021). "Moreover, the overexpression of GAS5 also produced increased chemosensitivity to cisplatin in vivo in a tumor formation model in nude mice." (PMID 33391419, 2021). "GAS5 performs its tumor suppressor function by various mechanisms of action." (PMID 35054253, 2021). "GAS5 dysregulation in other cancers 32, 58 and non-tumor diseases 59, 60 had also been reported." (PMID 33391419, 2021). "Interestingly, this dual role of KLHDC7B and GAS5 during tumor progression has also been found in other studies." (PMID 33987102, 2021). "Long noncoding RNA GAS5 (GAS5) has been proved to be closely related with tumor progression." (PMID 33976738, 2021).
tumor (continued). "In addition, the existing literature has proven that GAS5 is expressed at low levels in many malignant tumors, exhibits tumor-suppressing characteristics, and participates in cell cycle regulation." (PMID 33682891, 2021). "Similarly, the tumor suppressor lncRNA GAS5 was shown to target Wnt/β-catenin signaling and attenuate ABCB-1-mediated adriamycin resistance via miR-221-3p/Dickkopf-related protein 2 (DKK2) pathway regulation." (PMID 32967267, 2020). "GAS5 is a recently characterized tumor suppressive long ncRNA (lncRNA) in multiple types of cancer." (PMID 33308258, 2020). "GAS5 could directly bind to miR-182-5p and inhibit tumor cell proliferation through the miR-182-5p/FOXO3a axis." (PMID 33076450, 2020). "The tumour volume of the GAS5 low-expression group was large." (PMID 32661236, 2020). "Studies done on A431 cells determined that GAS5 promoted the proliferation and survival of tumor cells, although its molecular targets are currently unknown." (PMID 32674318, 2020). "Finally, a connection between GAS5 and miR-23a has been reported, where miR-23a was found to suppress GAS5 expression and enhance tumor cell proliferation and tumorigenesis." (PMID 33076450, 2020). "GAS5 under-expression was also related to tumor progression and proliferation." (PMID 33076450, 2020). "As a tumor marker, GAS5 is widely used in the prediction of a variety of tumor prognosis." (PMID 32069387, 2020). "In addition, GAS5 overexpression induced G0/G1 cell cycle arrest, apoptosis and cisplatin chemosensitivity, indicating its tumor suppressor effect." (PMID 32854207, 2020). "LncRNA GAS5, acts as a tumor suppressor, can block DDP resistance in CC via miR-21." (PMID 32489326, 2020). "Additionally, GAS5 suspected of sequestering hsa-miR-135b-5p in NSCLC tumor tissues and cell lines (A549 and H1975)." (PMID 32438606, 2020). "Apoptosis induced by GAS5 was certified by several tumor researches, but in this study, we didn’t detect apoptosis inducing effect of GAS5 after transfection." (PMID 32194641, 2020). "Research discovered that GAS5 overexpression could decrease the tumour growth, volume as well as weight of nude mice in vivo experiment." (PMID 32661236, 2020). "Interestingly, GAS5 can activate pyroptosis, which, as mentioned in the cell death paragraph, triggers an excessive inflammatory response, collaborating with tumor progression." (PMID 32326249, 2020). "mTOR negatively regulates GAS5 expression, which induces tumor cell proliferation." (PMID 32413995, 2020). "Finally, significantly decreased expression of GAS5, a tumor suppressor usually induced by stress (e.g., cell-to-cell contact inhibition, serum deficiency), was observed in cSCC tissue samples, in contrast to normal skin." (PMID 32674318, 2020). "Finally, miR-222 was reported to directly bind to GAS5 similarly, as in all previous cases, suppressing tumor cell proliferation." (PMID 33076450, 2020). "In addition, GAS5 and miR-135b reversely correlated and as reported in other tumors, GAS5 over-expression reduces miR-135b expression and, thus, inhibits tumor cell proliferation." (PMID 33076450, 2020). "The tumor suppressive role of GAS5 was recently supported by others as well, and all clues suggest that GAS5 could be used a promising biomarker for disease diagnosis, tumor progression, or even as a therapeutic marker." (PMID 33076450, 2020). "Among lncRNAs with tumor suppressor function is Growth arrest-specific 5 (GAS5)." (PMID 32967267, 2020). "Additionally, GAS5 appeared to be a direct target of miR-221/222, suppressing tumor proliferation and enhancing tumor cell apoptosis." (PMID 33076450, 2020).
tumor (continued). "In particular, this study showed that GAS5 has tumor suppressor activity since it could suppress tumor growth, while, when silenced, tumor cells recovered and increased their proliferation rate." (PMID 33076450, 2020). "In addition, it was found that GAS5 sponges miR-203a and miR-221, thus suppressing tumor growth and inhibiting tumor invasion." (PMID 33076450, 2020). "Thus, LncRNA GAS5 functions as a tumor-suppressive sponge through the GAS5-miRNA-23a-ATG3 axis to control the autophagy pathway." (PMID 31597272, 2019). "The low GAS5 expression group showed a significantly increased tumor size." (PMID 30606744, 2019). "Without functional smORFs and without a functional riborepressor, it is difficult to explain how the rodent Gas5 gene can function as a tumor suppressor, as the original 1988 publication contends, unless it is the snoRNA elements that provide the tumor suppressor function of the mouse Gas5 gene." (PMID 31533355, 2019). "New evidence shows that exosome-enriched lncRNAs may have special effects on cancer development; our data suggested that changing GAS5 content in tumor cell-derived exosomes affects the functions and phenotypes of HUVECs." (PMID 31186629, 2019). "Furthermore, in vivo assay demonstrates that overexpression of GAS5 significantly impaired tumor growth with a concomitant decline in cell viability and tumor volume compared with that in control group." (PMID 31619268, 2019). "Tumor suppressive lncRNAs (GAS5, MEG3, FER1L4 and LINC00672) and oncogenic lncRNAs (CCAT2, BANCR, NEAT1, MALAT1, H19, Linc-RoR, TUG1, TDRG1 and PCGEM1) may be a few such examples." (PMID 30781521, 2019). "In addition, there are reports that GAS5 acts as a tumor suppressor by modulating the expression of the oncogene cyclin-dependent kinase 6, but the specific regulatory mechanisms have not been elaborated, and further studies are needed to confirm." (PMID 30606744, 2019). "LncRNA GAS5 (GAS5) is identified as a tumor suppressor involved in several cancers." (PMID 31182630, 2019). "The detection of tumor size and weight showed that the volume of xenograft tumors with SGC-7901 cells expressing GAS5 was smaller than that of the control group, and miRNA-106a-5p overexpression partially inversed the roles of GAS5 overexpression in GC tumor formation." (PMID 31182630, 2019). "Furthermore, GAS5 acts as tumour suppressor and has been suggested as a potential target for diagnosis and therapy of OC." (PMID 31182053, 2019). "GAS5 acted as a tumor suppressor in HCC invasion in a competing endogenous RNA manner." (PMID 30733959, 2019). "For instance, GAS5 has been reported as a crucial tumour suppressor in a variety of human cancers." (PMID 30853980, 2019). "Further, expression of GAS5 increased as the tumor progressed." (PMID 31740660, 2019). "Most studies reported that GAS5 played a tumor suppressor role in CRC." (PMID 30902880, 2019). "We used STARBASE 2.0 software to predict the potential miRNAs that could bind both GAS5 and PTEN; among them, the target genes of miR-29-3p were significantly enriched in tumor-associated signaling pathways." (PMID 31186629, 2019). "GAS5 as a ceRNA competes with PDCD4 to bind to miR-21, and the depletion or overexpression of GAS5 could lead to the downregulation or upregulation of PDCD4 levels in tumor cells." (PMID 31620370, 2019). "Afterwards, GAS5 has been found to be aberrantly expressed in many cancers and other diseases and plays crucial roles in pathological processes, such as cell proliferation, apoptosis, tumor growth and metastasis." (PMID 31182630, 2019). "GAS5 was identified as a tumor suppressor lncRNA in a variety of malignant tumors." (PMID 30606744, 2019). "In addition, the expression levels of GAS5 in tumor tissues of young BC women (ages <45 years) are significantly lower than in that of old BC women patients (ages >45 years)." (PMID 31480503, 2019).
tumor (continued). "Moreover, several studies have indicated that Gas5 acts as a tumour suppressor by regulating apoptosis appropriately, such as in breast cancer and renal cell carcinoma." (PMID 29490650, 2018). "Finally, we assessed the effects of GAS5 on bladder xenograft tumors and its effect on GA-induced growth inhibition of bladder xenograft tumor." (PMID 29445179, 2018). "Considering disease outcome, GAS5 loss was strongly associated with higher risk for NMIBC early relapse and progression to invasive disease stages following tumour resection, independently of tumour stage, grade, EORTC-risk score and patient’s age and gender." (PMID 30374124, 2018). "LncRNA GAS5 may function as a suppressor of tumor progression by inducing inflammasome formation, which, in turn, actives inflammatory processes, to induce cell pyroptosis, a process characterized as programmed cell death." (PMID 29229673, 2018). "It is obvious that tumor growth was inhibited by GA and promoted by knockdown of GAS5." (PMID 29445179, 2018). "In addition, these experiment models and animal investigations also supported the role of lncRNA GAS5 as tumor suppressor." (PMID 29229673, 2018). "Moreover, Gas5 levels are also significantly reduced in many types of cancer cells and increasingly, studies on Gas5 as a tumour suppressor are being carried out in the cancer field." (PMID 29490650, 2018). "Overall, our findings clearly support the use of a NMIBC prognosis prediction model, based on GAS5 expression and the independent clinicalpathologic prognostic markers of NMIBC, namely tumour stage, tumour grade and EORTC-risk stratification, using biopsy specimens of TURBT-treated TaT1 patients." (PMID 30374124, 2018). "The long non‐coding RNA GAS5 has been reported as a tumor suppressor in many cancers." (PMID 29745062, 2018). "GAS5, a tumor suppressor lncRNA, has been extensively studied in multiple cancers." (PMID 29745062, 2018). "Additionally, lncRNA knockdown studies have revealed a role for growth arrest-specific 5 (GAS5) in tumor cell quiescence and the modification of cell proliferation and PVT1 oncogene (PVT1) in the regulation of apoptosis and cell proliferation." (PMID 30060501, 2018). "Similarly, the model integrating GAS5 loss offers the highest clinical benefit for the prediction of NMIBC progression for threshold probabilities >0%, compared to tumour stage, grade, EORTC-risk group and recurrence at FFC model." (PMID 30374124, 2018). "The tumor volume of pcDNA3.1/Gas5 group is dramatically decreased compared with pcDNA3.1 group." (PMID 29423063, 2018). "LncRNA Gas5 can inhibit cell proliferation and promote apoptosis, which may provide the basis of its action as a tumor suppressor." (PMID 29308053, 2018). "We observed that the tumor size in Gas5 KD mESC-formed teratomas was much smaller than the control, indicating that Gas5 might affect mESCs proliferation." (PMID 29562912, 2018). "Also, another study provided evidence that overexpression of Gas5 can act as a tumor suppressor for renal carcinoma cell (RCC), providing a potentially valuable therapeutic approach for RCC." (PMID 29308053, 2018). "A previous study suggested that lncRNA Gas5 was an important tumor suppressor and could serve as a biomarker in CRC cells." (PMID 29308053, 2018). "Functional studies have validated that lncRNA Gas5, acting as a tumor repressor could potentially inhibit proliferation and promote apoptosis of several cell types." (PMID 29308053, 2018). "In our study, GAS5 was equally expressed in MT and TT and did not reveal any association with survival or tumour stage." (PMID 30205577, 2018). "Multivariate COX regression analysis showed that the Gas5 expression, distant metastasis, tumor differentiation and TNM staging could serve as independent prognostic factors in patients with CRC." (PMID 29308053, 2018). "In other words, over-expressed GAS5 can inhibit tumor growth and induce cell apoptosis, which may be regarded as an anti-oncogene for OSCC." (PMID 29296179, 2017).